SPP1 (secreted phosphoprotein 1)
Diseases named in the same sentence as SPP1 in open-access papers (continued):
Sharing a sentence is not in itself a finding about the gene and the disease.
Hyperoxaluria (9 papers, 2015 to 2025). Increased excretion of oxalates in the urine. "Our findings suggest that the elevated expression of SPP1 induced by hyperoxaluria may enhance biomineralization in the kidneys, ultimately contributing to CaOx stone formation." (PMID 39452123, 2024).
interstitial lung disease (9 papers, 2015 to 2025). A diverse group of lung diseases that affect the lung parenchyma. "SPP1, on the other hand, is a biomarker of fibrosis in NASH, primary sclerosing cholangitis, and of interstitial lung disease progression in SSC." (PMID 37706477, 2023).
invasive breast carcinoma (9 papers, 2010 to 2024). A carcinoma that infiltrates the breast parenchyma. "In the Finak breast data set, invasive breast cancers with recurrence over 3 years (n = 59) showed fourfold increase in SPP1 compared with normal (n = 6), with p = 1.06E-4." (PMID 26821678, 2016). "We further analyzed Kaplan–Meier survival curves generated from an invasive breast carcinoma dataset (GSE58644), which showed a notable drop in the overall survival after 5 years for patients with high Spp1-expressing tumors." (PMID 39448577, 2024). "From gene signature analysis on invasive breast carcinoma stroma (GSE9014), we observed a positive correlation between CD206+ pro-tumorigenic macrophages and Spp1 from the epithelial tumor compartment." (PMID 39448577, 2024).
pancreatic adenocarcinoma (9 papers, 2007 to 2026). "13/14 of these cancer-related pathways, including pancreatic adenocarcinoma signaling, were in a direction suggestive that SPP1 loss protects against tumor progression in human pancreatic duct cells." (PMID 34009124, 2021).
psoriasis (9 papers, 2019 to 2025). An autoimmune condition characterized by red, well-delineated plaques with silvery scales that are usually on the extensor surfaces and scalp. "Interestingly, serum levels of SPP1, in conjunction with other proteins, were recently identified by machine learning as potential biomarkers to distinguish patients with PsA from those with psoriasis alone." (PMID 37137278, 2024).
renal carcinoma (9 papers, 2017 to 2025). A carcinoma arising from the epithelium of the renal parenchyma or the renal pelvis. "Co-culture experiments revealed that the increased expression of SPP1 in renal cancer cells led to a marked polarization of APOE+ M2-like macrophages, elevated the levels of immunosuppressive markers like APOE and CEBPD." (PMID 40303328, 2025). "Next, we employed WB analysis to elucidate the impact of SPP1 OE in renal cancer cells on macrophage." (PMID 40303328, 2025). "Similar to renal cancer, samples in skin cancer also showed significant overexpression of SPP1 with higher stages." (PMID 39857756, 2025). "They discovered two subgroups: VEGFA + SPP1 +, which is significantly overexpressed in renal cancer and linked to tumor angiogenesis and growth, and HLA-DR + CD74 +, which is present in renal cancer and contributes to antitumor immunity by activating T cells." (PMID 41035074, 2025). "Furthermore, we utilized the Vector Co-cultured CM, the SPP1 OE Co-cultured CM group, and the SPP1 OE Co-culture CM+APOE Ab group to investigate the malignant progression of renal cancer cells in the presence of APOE+ M2-like macrophages." (PMID 40303328, 2025). "Additionally, YBX1 is capable of interacting with G3BP1 to promote SPP1 upregulation, resulting in renal cancer invasion and metastasis." (PMID 34758833, 2021). "In renal cancer, tumorous samples in GSE167573 displayed a large number of cellular developmental pathways, including extracellular matrix organization, another key feature of SPP1 functionality." (PMID 39857756, 2025).
sarcoidosis (9 papers, 2011 to 2025). Sarcoidosis is a multisystemic disorder of unknown cause characterized by the formation of immune granulomas in involved organs. "Studies investigating SPP1 gene polymorphisms and sarcoidosis susceptibility have identified several single-nucleotide polymorphisms (SNPs) associated with the disease, including rs11730582, rs11728697, and rs4754." (PMID 40559389, 2025). "Research indicates that single-nucleotide polymorphisms (SNPs) in the SPP1 gene are strongly associated with susceptibility to pulmonary lesions in sarcoidosis, which also encompasses the EMT pathway." (PMID 41293726, 2025). "SPP1 is raised in the blood and granulomatous tissue of individuals with sarcoidosis, elucidating the EMT pathway in disease development." (PMID 41293726, 2025). "As previously noted, SPP1 undergoes post-translational modifications, and research suggests that carboxyl-terminal SPP1 (C-SPP1) counteracts full-length SPP1 (F-SPP1) in sarcoidosis." (PMID 40559389, 2025). "Interestingly, this study also reports that serum SPP1 levels were higher in subjects with TB compared to subjects with sarcoidosis." (PMID 40559389, 2025). "Elevated serum SPP1 levels have been observed in patients with sarcoidosis, and increased SPP1 expression has been detected within sarcoid granulomas, although the serum level of SPP1 may be lower than that of interstitial pneumonia (IP) patients." (PMID 40559389, 2025). "In addition to sarcoidosis, SPP1 is also elevated in the histiocytes of various other granulomatous lung disorders, underscoring its broader role in granuloma formation and ILD pathogenesis." (PMID 40559389, 2025). "Furthermore, although SPP1-expressing macrophages were detectable in sarcoidosis, IFNG-expressing T cells were a more defining feature of sarcoidosis compared with NL and NXG." (PMID 39989459, 2025). "(iv) SPP1 in Noninfectious Granulomatous Lung Diseases: Sarcoidosis is the most common noninfectious granulomatous lung disease, characterized by immune cell-driven inflammation and granuloma formation." (PMID 40559389, 2025). "However, upregulation of SPP1 was more modest, and unlike NL and NXG macrophages, sarcoidosis lesional macrophages strongly overexpressed APOE, VAT1, TLR8, and ALDH1A1 among other genes." (PMID 39989459, 2025).
sarcoma (9 papers, 2010 to 2025). A usually aggressive malignant neoplasm of the soft tissue or bone. "In some data sets, SPP1 expression was lower in kidney cancer and sarcoma compared with that in normal tissues." (PMID 35067176, 2022). "Moreover, we calculated the infiltration scores of exhausted T cells (ex_T), OLR1 + macrophages (OLR1 + MC), and SPP1+macrophages (SPP1 + MC) in sarcomas treated with pazopanib (GSE156344)." (PMID 39658531, 2024). "Pseudotime analysis indicated that SPP1+ macrophages were a poor‐differentiated cell subset, while OLR1+macrophages were a high‐differentiation cell subset, which suggesting sarcomas microenvironment also induces matured macrophages phenotype transfer." (PMID 39658531, 2024). "Previous studies have reported that CXCL9:SPP1 macrophage polarity is a good choice for selecting anti‐ or pro‐tumor macrophages in sarcoma, we also examined changes in the CXCL9:SPP1 polarity of PBS‐BMDMs and OCDM‐BMDMs after 24 h of coculture with apoptotic OS cells." (PMID 40056029, 2025).
systemic sclerosis (9 papers, 2021 to 2025). A chronic disorder, possibly autoimmune, marked by excessive production of collagen which results in hardening and thickening of body tissues. "Thus, to compare the expression of CCL4 and SPP1 in systemic sclerosis myeloid cells versus healthy skin myeloid cells, scRNA-seq data from all systemic sclerosis myeloid cells were binned together and compared to all healthy skin–derived myeloid cells." (PMID 39989459, 2025). "MicroRNA-27a-3p negatively regulates SPP1 to inhibit lung and skin fibrosis of systemic sclerosis." (PMID 38041130, 2023). "This analysis revealed that there was no significant and meaningful (fold change [FC] > 2) upregulation in the expression of SPP1, CCL4, CCL5, and CXCL9 in systemic sclerosis myeloid cells." (PMID 39989459, 2025).
type 1 diabetes (9 papers, 2011 to 2025). "While this upregulation cannot be specifically linked to beta cells in this study, it is interesting to speculate that an age-correlated upregulation of SPP1 could have a protective effect, contributing to why type 1 diabetes pathogenesis progress slower with higher age at onset." (PMID 33711030, 2021).
allergic asthma (8 papers, 2014 to 2025). A asthma with a basis in a pathological type I hypersensitivity reaction. "Furthermore, Samitas found that SPP1/Osteopontin plays a critical role in the modulation of allergic asthma by preserving the homeostasis of the gut-lung axis." (PMID 41293726, 2025).
aneurysm (8 papers, 2014 to 2025). Bulging or ballooning in an area of an artery secondary to arterial wall weakening. "Our present study altogether suggested the pathogenic relevance between intracranial atherosclerosis and non-branching site BBAs and further emphasized the significance of SPP1-mediated ligand–receptor interaction in aneurysm progression." (PMID 35874788, 2022). "We selected and validated the genes randomly (Lrrc17, Gxylt2, Mfsd2a, Scube and Ank2) and based on their role in aneurysms (Mmp12, Spp1, Ctss) or cardiovascular complications (Mfap4, Igfbp2) or inflammatory signalling pathways (Ccls and Ccrs)." (PMID 30677223, 2019). "In addition, in SPP1-null mice, there is evidence of less leukocyte infiltration and lower matrix proteinase activity at the sites of aneurysms." (PMID 37698712, 2023). "In intracranial aneurysm studies, SPP1 was not considered a marker of tumor-associated macrophages; SPP1 was instead first described in Shi’s aneurysm genome profile work as a major contributor in extracellular matrix reconstruction and immune cell recruitment." (PMID 35874788, 2022). "In all, SPP1 and MIF signaling between macrophage and SMC subsets might exert an essential role during aneurysm progress among different species." (PMID 36703732, 2022).
depression (8 papers, 2021 to 2025). "The pathogenesis of depression was associated with changes in SPP1, Plasminogen activator inhibitor 1, CCNB1 protein, CCL3, and other genes." (PMID 37932972, 2023). "Integrated bioinformatics analysis identified the SPP1 signaling pathway as a potential key regulator in post‐ICH depression pathogenesis." (PMID 41345421, 2025). "Our study is the first to demonstrate the critical role of SPP1 signaling in post‐ICH depression through modulation of the Nrf2/BDNF pathway, providing novel therapeutic targets for clinical management of this debilitating neuropsychiatric sequela." (PMID 41345421, 2025). "We screened depression-related DEGs in the GEO database and combined them with the TCMSP database in this study and concluded that the occurrence of depression was closely related to changes in SPP1, SERPINE1, CCNB1, CCL3, and other genes." (PMID 37932972, 2023). "In light of these mechanisms, our study employs an intracerebral hemorrhage (ICH) murine model to investigate SPP1's therapeutic potential in ameliorating neurological deficits, cognitive dysfunction, and affective disorders including depression and anxiety‐like behaviors." (PMID 41345421, 2025). "Among them, the degree values of VTN, SPP1, plasminogen activator inhibitor 1 (SERPINE1), membrane spanning 4-domains a2, HIST2H2AC, and other genes were high in the whole network; therefore, these genes can be considered crucial for the development of depression." (PMID 37932972, 2023).
diabetic retinopathy (8 papers, 2010 to 2025). "Although the exact implications for diabetic retinopathy remain open at this point, the loss of a SPP1, which has been described to rescue photoreceptors and to be induced by neuroprotective factor GDNF, is an important finding of our study and deserves further investigation in our opinion." (PMID 34046254, 2021). "Elevated levels of OPN, a glycosylated, secreted phosphoprotein (SPP1), is found in the vitreous fluid and retina of diabetic patients irrespective of the presence of diabetic retinopathy." (PMID 39480896, 2024).
endothelial dysfunction (8 papers, 2020 to 2025). In vascular diseases, endothelial dysfunction is a systemic pathological state of the endothelium (the inner lining of blood vessels) and can be broadly defined as an imbalance between vasodilating and vasoconstricting substances produced by (or acting on) the endothelium. "Lastly, while we focused on AP1, FN1, and SPP1 in nicotine-induced endothelial dysfunction, the broader regulatory network—including their roles in cytoskeletal signaling, focal adhesion dynamics, and ECM–receptor interactions—remains unexplored." (PMID 40722963, 2025).
influenza infection (8 papers, 2011 to 2025). "In previous studies mice lacking SPP1 and CCL5 were found to clear influenza infection with no adverse effects, while mice lacking CCR2 survived infection by a mouse-adapted influenza A virus that killed wild-type mice." (PMID 22189154, 2011).
oral cancer (8 papers, 2012 to 2025). "Significantly, OASL|SPP1 was the most strongly and negatively correlated with the prognosis of oral cancer." (PMID 35804390, 2022). "The gene knockdown experiment in an oral cancer cell line and clinical data analysis showed that SPP1 is important for oral cancer invasion and metastasis in this study." (PMID 30459815, 2018). "We further tried to explore the correlation of expression of CCND1, JUN and SPP1 with oral cancer metastasis through statistically analyzing the clinic data in the literature." (PMID 30459815, 2018). "Silencing expression of CCND1, JUN and SPP1 in the human oral cancer cell line OECM-1 confirmed that those genes play essential roles in oral cancer cell invasion." (PMID 30459815, 2018). "We focused on those 28 common DEGs that show consistent changes in both datasets and defined a “metastasis signature”: CCND1, JUN and SPP1 for oral cancer lymph node metastasis." (PMID 30459815, 2018). "Our study identified a novel “focal adhesion”-related gene signature (CCND1, JUN and SPP1) that might be applicable for diagnosis of oral cancer metastasis to lymph nodes." (PMID 30459815, 2018). "Our study identified a unique gene signature – CCND1, JUN and SPP1 – which may be involved in oral cancer lymph node metastasis." (PMID 30459815, 2018). "The result further supports the hypothesis that the focal adhesion-related gene signature (CCND1, JUN and SPP1) is important for oral cancer invasion." (PMID 30459815, 2018). "In sum, this study identifies a unique gene signature – CCND1, JUN and SPP1 – which could be a new early biomarker for diagnosing oral cancer lymph node invasion and metastasis." (PMID 30459815, 2018). "Our study identified a novel focal adhesion-related gene signature (CCND1, JUN and SPP1) that might be important for oral cancer metastasis to lymph nodes." (PMID 30459815, 2018). "Further, we selected genes (ACP5, SPP1, and MMP12) from our study on late-stage oral cancer buccal mucosa patients." (PMID 41410801, 2025). "To confirm the function of CCND1, JUN and SPP1 in oral cancer cell invasion, we knocked down expression of CCND1, JUN and SPP1 through siRNA in the human oral cancer cell line OECM-1 and examined the alteration of cell invasion ability." (PMID 30459815, 2018). "Through bioinformatics analysis of the gene expression profile of oral cancer metastatic and non-metastatic lymph nodes and primary tumors, we identified a new oral cancer metastatic gene signature: CCND1, JUN and SPP1." (PMID 30459815, 2018). "We have not found similar gene expression data of CCND1 and SPP1 in oral cancer metastasis." (PMID 30459815, 2018).
pancreatic ductal adenocarcinoma (8 papers, 2015 to 2025). An infiltrating adenocarcinoma that arises from the epithelial cells of the pancreas. "In pancreatic ductal adenocarcinoma (PDAC), PLXDC1+ tumor-associated pancreatic stellate cells (TPSCs) are located adjacent to LRRC15+ myCAFs and SPP1+ macrophages, collectively forming a desmoplastic and immunosuppressive perimeter that promotes CD8+ TEX." (PMID 41425545, 2025).
papillary thyroid cancer (8 papers, 2014 to 2021). "As far as the papillary thyroid carcinomas are concerned, FOS, FOSB and EGR1 genes were down-regulated, like CBX7, while SPP1, SPINK1 and STEAP1 were up-regulated." (PMID 24865347, 2014). "As it has been noted on previous work: CST6, CXCL14, DHRS3, and SPP1 are regulated by BRAF signaling and may play a role in papillary thyroid carcinoma pathogenesis." (PMID 25887408, 2015).
tongue cancer (8 papers, 2009 to 2023). A malignant neoplasm affecting the tongue. "The present study demonstrated that SPP1 was significantly upregulated in tongue cancer, suggesting that FN1 and SPP1 play important roles in the development of tongue cancer." (PMID 32236620, 2020). "We found a negative association between DDX5 expression and Macro_spp1 (M2 type) infiltration in the TME of tongue cancer tissues." (PMID 38136426, 2023). "In addition, previous research found inhibition of the SPP1 gene may have therapeutic benefits for tongue cancer and may be a useful target for therapy." (PMID 36303551, 2022). "It was reported that lacking of SPP1 inhibits progression by mediating the PI3K/Akt signaling pathway in tongue cancer." (PMID 36038839, 2022).
triple-negative breast carcinoma (8 papers, 2018 to 2025). An invasive breast carcinoma which is negative for expression of estrogen receptor (ER), progesterone receptor (PR), and human epidermal growth factor receptor 2 (HER2). "This study investigated the role of SPP1 in the prognosis of triple-negative breast cancer (TNBC) and its potential involvement in immune regulation." (PMID 39727934, 2024). "In this study, we focused on analyzing the correlation between SPP1 expression and the prognosis of triple-negative breast cancer (TNBC)." (PMID 39727934, 2024). "Notably, SPP1 + macrophages and M2 macrophages exhibited higher R o/e indexes in triple-negative breast cancer (TNBC)." (PMID 41325308, 2025). "Notably, SPP1 + macrophages also represented a significant proportion in triple-negative breast cancer." (PMID 41325308, 2025). "Importantly, follow-up analysis by real-time PCR confirmed that a number of genes associated with osteomimicry (CTSK, SPP1 and RANK) were upregulated in ER+ and triple-negative breast cancer cell lines and PDXs that had metastasised to bone, compared with their associated primary tumours." (PMID 31783893, 2019). "This list was further filtered through a triple-negative breast cancer (TNBC) scRNA-Seq dataset by applying a stringent criteria selection (i.e., high expression restricted to the macrophage cluster), leading to 4 genes: SPP1, APOC1, FCER1G, and MMP9." (PMID 39808498, 2025).
allergic rhinitis (7 papers, 2010 to 2026). Inflammation of the nasal mucous membranes caused by an IgE-mediated response to external allergens. "In the East Asian population, the expression level of SPP1 was significantly negatively correlated with age, hay fever, or allergic rhinitis diagnosed by a doctor." (PMID 41056019, 2026). "In allergic rhinitis, upregulated SPP1 expression induced by leptin facilitates Th2 inflammation, and this process is mediated by α4 integrin and PI3K/Akt pathway." (PMID 31281837, 2019).
calcification (7 papers, 2012 to 2025). Process by which organic tissue becomes hardened by the physiologic deposit of calcium salts. "Vascular and renal calcifications have been also reported in mice with global deletion of osteopontin (Spp1−/−) following the administration of a high-phosphate diet or the induction of CKD." (PMID 40471241, 2025). "Increased SPP1 mRNA expression and plasma osteopontin levels have been linked with cardiac allograft vascular disease (CAVD), whereas it has been reported to have inhibitory effects on arterial calcification." (PMID 33101359, 2020).
cerebral infarction (7 papers, 2011 to 2024). An ischemic condition of the brain, producing a persistent focal neurological deficit in the area of distribution of the cerebral arteries. "Spp1 expression is increased following brain infarct and in vessels with blood—brain barrier impairment." (PMID 26556046, 2015).